CNTNAP1 (contactin associated protein 1)
Description:
Required, with CNTNAP2, for radial and longitudinal organization of myelinated axons. Plays a role in the formation of functional distinct domains critical for saltatory conduction of nerve impulses in myelinated nerve fibers. Demarcates the paranodal region of the axo-glial junction. In association with contactin involved in the signaling between axons and myelinating glial cells.
Synonyms: Caspr; NRXN4; p190; CNTNAP; CHN3
Tractability: Antibody: UniProt predicts a signal peptide or a membrane-spanning region. PROTAC: ubiquitination databases record sites on it.
Gene: Protein-coding gene on chromosome 17 (42,682,531 to 42,699,993, forward strand). Ensembl gene ENSG00000108797.
Subcellular location: Membrane; Cell junction, paranodal septate junction
Subcellular location (Human Protein Atlas): Nucleoplasm
Pathways (Reactome):
Developmental Biology: Neurofascin interactions
Gene Ontology:
Molecular function: protein binding; SH3 domain binding; signaling receptor activity
Biological process: central nervous system myelination; myelination in peripheral nervous system; neuron projection morphogenesis; paranodal junction assembly; cytoskeleton organization; myelination; nervous system development; neuronal action potential propagation; protein localization to juxtaparanode region of axon; protein localization to paranode region of axon; signal transduction; axonogenesis; central nervous system development; mitochondrion organization; neuromuscular junction development, skeletal muscle fiber; neuromuscular process; neuromuscular process controlling balance; neuromuscular process controlling posture; paranodal junction maintenance; postsynaptic density organization; regulation of synapse maturation
Cellular component: paranode region of axon; plasma membrane; synapse; glutamatergic synapse; membrane; paranodal junction
Genetic constraint (gnomAD): Loss-of-function variants: 80 observed, 166.61 expected, observed/expected ratio (o/e) 0.48, 90% interval 0.4 to 0.58. The upper end of that interval is the gene's LOEUF score, 0.58, which puts it in group 2 of 6, group 1 being the genes least tolerant of losing a copy. Missense variants: 1,464 observed, 1,926.1 expected, observed/expected ratio (o/e) 0.76, 90% interval 0.73 to 0.79. Synonymous variants: 695 observed, 764.14 expected, observed/expected ratio (o/e) 0.91, 90% interval 0.85 to 0.97.
Homologues: Orthologues: chimpanzee CNTNAP1 (100% identical), macaque CNTNAP1 (99% identical), pig CNTNAP1 (96% identical), dog CNTNAP1 (95% identical), rabbit CNTNAP1 (95% identical), mouse Cntnap1 (93% identical), guinea pig CNTNAP1 (92% identical), rat Cntnap1 (92% identical), tropical clawed frog cntnap1 (55% identical). Paralogues in human: CNTNAP2 (42% identical), CNTNAP5 (36% identical), CNTNAP4 (36% identical), CNTNAP3 (34% identical), CNTNAP3B (34% identical), NRXN2 (21% identical), NRXN3 (20% identical), NRXN1 (20% identical), CUBN (13% identical), CNTNAP3C (12% identical), HEPHL1 (11% identical), F8 (11% identical), and 23 more.
Diseases named in the same sentence as CNTNAP1 in open-access papers:
CNTNAP1 is named in the same sentence as 86 diseases in open-access papers, as found by Europe PMC text mining. Sharing a sentence is not in itself a finding about the gene and the disease. The quoted sentences say what the papers report.
chronic inflammatory demyelinating polyneuropathy (9 papers, 2016 to 2025). "One month later, he was diagnosed with chronic inflammatory demyelinating polyneuropathy associated with anti-contactin-associated protein 1 antibody." (PMID 35139901, 2022). "We present the case of a 66-year-old Chinese man who concomitantly developed chronic inflammatory demyelinating polyneuropathy with anti-contactin-associated protein 1 antibody and bile duct hamartomas in liver, which are rarely reported in China." (PMID 35139901, 2022). "Anti-NF155 and anti-contactin-1 IgG4 are the most frequently detected antibodies, representing 1 to 20% of chronic inflammatory demyelinating polyradiculoneuropathies, with anti-contactin-associated protein-1 and anti-NF140/186 syndromes occurring less frequently." (PMID 39854764, 2025).
neuropathy (7 papers, 2018 to 2025). A disorder affecting the nervous system that manifests with pain, tingling, numbness, and/or muscle weakness. "In the current study, we reported 2 patients diagnosed as neuropathy caused by potentially novel CNTNAP1 mutations." (PMID 33148880, 2020). "Neuropathy workup was integrated by anti‐neurofascin 155, anti‐panneurofascin, anti‐contactin 1 (CNTN1), and anti‐contactin associated protein 1 (CASPR1) antibodies and next‐generation sequencing for CMT, which were negative." (PMID 40685796, 2025). "To date, only 29 CNTNAP1-related neuropathy cases were reported on PubMed since 2014." (PMID 33148880, 2020).
Ataxia (5 papers, 2020 to 2023). Ataxia refers to impaired coordination of voluntary muscle movement. "Cntnap1-KO mice exhibit tremors, paresis, ataxia, and failed formation of normal paranodal junctions." (PMID 33148880, 2020).
Intellectual disability (3 papers, 2016 to 2019). "Several genes related to intellectual disability (Dcaf17, Myst4, Park2, Rbfox1) were found to be hypo-methylated in male pups, and genes (Pfn1, Cntnap1, Drp2) related to normal function of the nervous system were hypo-methylated in female pups from the HMFA group." (PMID 27199632, 2016).
polyneuropathy (3 papers, 2020 to 2025). A disease or disorder affecting more than one nerve. "Here we confirm homozygosity for the CNTNAP1 variant in Great Dane dogs with polyneuropathy supported by electrodiagnostic and tissue biopsy sample investigations." (PMID 40622077, 2025).
epilepsy (2 papers, 2011 to 2019). A brain disorder characterized by episodes of abnormally increased neuronal discharge resulting in transient episodes of sensory or motor neurological dysfunction, or psychic dysfunction. "Interestingly, these patients have a similar phenotype to patients with CNTNAP1/CASPR1 mutations; however, without any epilepsy, which has been reported in CASPR1-mutated patients." (PMID 31501903, 2019).
cognitive deficits (1 paper, 2020). "CNTNAP1 deficiency might contribute to the global cognitive deficits found in CNTNAP1-related disease patients." (PMID 33148880, 2020).
Visual impairment (1 paper, 2018). "Hearing and visual impairment are not a widely reported finding in CHN in association with any of these other genes and again this appears to be a specific finding in CNTNAP1-CHN although it is not seen in all patients." (PMID 29511323, 2018).
tumor (9 papers, 2011 to 2025). "In this tumor, the expression of the CNTNAP1 gene was positively associated with cancer-associated fibroblasts." (PMID 35742950, 2022). "Previous studies have identified genes such as lncRNA AGAP2-AS1 and mRNA CNTNAP1, which influence M2 macrophage polarization, subsequently impacting the tumor microenvironment and progression." (PMID 40221501, 2025).
infection (6 papers, 2018 to 2024). The state of being infected such as from the introduction of a foreign agent such as serum, vaccine, antigenic substance or organism. "Two mRNAs were down-regulated in all treatment groups at the later time points post-infection, namely, CNTNAP1 and NR4A1, while twenty mRNAs were up-regulated in all later time point treatment groups, including IFI6, LY6E, MX1, OASL, STAT1, and CMPK2." (PMID 38675946, 2024).
neurodegenerative disease (1 paper, 2020). A disorder of the central nervous system characterized by gradual and progressive loss of neural tissue and neurologic function. "Our results represent the first large animal model for a CNTNAP1-related neurodegenerative disease." (PMID 33261176, 2020).
neurological disorders (1 paper, 2020). "Human patients with other CNTNAP1 homozygous frameshift or nonsense variants show a more severe disorder with early-onset neurological disease, including severe respiratory compromise and early lethality, while those carrying missense variants can survive beyond infancy." (PMID 33261176, 2020).
CNTNAP1 also shares sentences with these, for which no sentence is quoted: leukemia (13 papers); acute lymphoblastic leukemia (12); chronic myeloid leukemia (9); breast carcinoma (5); cancer (5); encephalitis (5); Tremor (4); autoimmune neuropathies (3); myasthenia gravis (3); autism (2); bacterial meningitis (2); E. coli infection (2); glioma (2); meningitis (2); nephrotic syndrome (2); peripheral neuropathy (2); psychiatric disease (2); sensory ataxia (2); acute inflammatory demyelinating polyneuropathy (1); acute leukemia (1); amyotrophic lateral sclerosis (1); anthrax (1); arthrogryposis (1); autism spectrum disorder (1); autoimmune encephalitis (1); Autoimmunity (1); B-cell lymphoblastic leukemia (1); bacteremia (1); bacterial infection (1); cervical cancer (1).
A further 44 diseases each share a sentence with CNTNAP1 in 1 paper.